BACH1 (BACH transcriptional regulator 1)
Diseases named in the same sentence as BACH1 in open-access papers (continued):
Sharing a sentence is not in itself a finding about the gene and the disease.
fibrosarcoma (1 paper, 2023). A malignant mesenchymal fibroblastic neoplasm affecting the soft tissue and bone. "It is composed of the BTB and CNC homolog 1 (Bach1) transcription factor and one of the three small musculoaponeurotic fibrosarcoma genes (MafF, MafG, or MafK)." (PMID 38131014, 2023).
Granuloma (1 paper, 2024). A compact, organized collection of mature mononuclear phagocytes, which may be but is not necessarily accompanied by accessory features such as necrosis. "Importantly, when we analysed tissue expression of BACH1 in both Mtb-infected humans and experimentally infected animals, we observed a strong spatial association of the protein with necrotic areas in granulomas." (PMID 38066332, 2024). "Solid granulomas from these animals showed strong Bach1 staining in the central myeloid cell enriched core compared with cells located at the periphery (cuff) of the lesion." (PMID 38066332, 2024).
head and neck squamous cell carcinoma (1 paper, 2022). A squamous cell carcinoma that arises from any of the following anatomic sites: lip and oral cavity, nasal cavity, paranasal sinuses, pharynx, larynx, and salivary glands. "The expression of BACH1 in Head and Neck squamous cell carcinoma (HNSC) has positive correlation to the infiltration of CD8+ T cells, B cells, neutrophils, macrophages, and myeloid dendritic cells, but no relative infiltration of CD4+ T cells." (PMID 35651942, 2022).
Intellectual disability (1 paper, 2026). "Chromosome 21 transcription factors BACH1, PKNOX1 and GABPA emerged as dosage-sensitive hubs regulating genes linked to intellectual disability." (PMID 41545595, 2026).
iron deficiency (1 paper, 2022). "Taken together with the enhanced BACH1 protein degradation by heme, these results demonstrated that iron deficiency, which leads to a decrease in heme, induces the expression of BACH1 at both transcriptional and post-translational steps." (PMID 36009179, 2022). "Since BACH1 is known to be induced by the hypoxic response, hypoxia-inducible factors may be involved in the increased transcription of BACH1 gene in response to iron deficiency." (PMID 36009179, 2022).
ischemia (1 paper, 2016). A hypoperfusion of the BLOOD through an organ or tissue caused by a PATHOLOGIC CONSTRICTION or obstruction of its BLOOD VESSELS, or an absence of BLOOD CIRCULATION. "Our results indicated that Bach1 upregulation impaired the blood flow recovery from hindlimb ischemia and this effect was accompanied both by increases in ROS and cleaved caspase 3 levels and by declines in the expression of cyclin D1 in the injured tissues." (PMID 27057283, 2016).
left ventricular hypertrophy (1 paper, 2021). Enlargement of the LEFT VENTRICLE of the heart. "Deletion of BACH1 caused significant reductions in left ventricular hypertrophy." (PMID 34054926, 2021).
Lewis Lung Carcinoma (1 paper, 2020). "Similar differences in the intratumoral blood vasculature were observed after subcutaneous inoculation of either BACH1-overexpressing ES2 cells or Bach1-overexpressing mouse D122 Lewis Lung Carcinoma cells." (PMID 32132179, 2020).
lumbar disc herniation (1 paper, 2025). "Notably, the transcription factor Bach1, which has been highly associated with ferroptosis in acute lung injury and lumbar disc herniation, was significantly elevated in the HA-TBI group and prominently featured in the upregulated region of the differential gene volcano plot for astrocytes." (PMID 39905004, 2025).
lymph node metastasis (1 paper, 2023). "Our study demonstrated the associations of both BACH1 protein antigen and BACH1 autoantibodies with lymph node metastasis in patients with ESCC." (PMID 36670112, 2023). "In this study, we found a novel anti-BACH1 IgG autoantibody that was significantly correlated with early-stage lymph node metastasis." (PMID 36670112, 2023). "We also found that serum anti-BACH1 autoantibodies are promising biomarkers for detecting early lymph node metastasis." (PMID 36670112, 2023). "Serum autoantibodies against BACH1 showed the highest discriminative capability for lymph node metastasis in ESCC." (PMID 36670112, 2023). "We validated the anti-BACH1 autoantibody findings by immunoblotting using a larger independent cohort, including 122 healthy controls, 39 early-stage ESCC patients, 50 ESCC patients without lymph node metastasis, and 78 ESCC patients with lymph node metastasis." (PMID 36670112, 2023).
lymphoma (1 paper, 2021). A malignant (clonal) proliferation of B- lymphocytes or T- lymphocytes which involves the lymph nodes, bone marrow and/or extranodal sites. "Our analyses revealed higher BACH1 expression in MCL than other lymphoma subtypes, and a significant positive correlation between BACH1 and CCND1 was also discovered in patients with MCL, implying a potential oncogenic role of BACH1." (PMID 34039348, 2021). "Intriguingly, further analysis of one published microarray dataset (GSE2350) revealed higher BACH1 levels in MCL patients compared with other subtypes of lymphomas, implying a potential oncogenic role of BACH1 in MCL." (PMID 34039348, 2021).
medulloblastoma (1 paper, 2021). A malignant, invasive embryonal neoplasm arising from the cerebellum. "The seven circRNAs, FKBP8, SMARCA5, GLIS1, BACH1, ZKSCAN1, CDYL, and OGDH, with a reduced expression in medulloblastoma versus cerebellum, while their corresponding linear mRNAs do not follow this change of expression pattern, were selected for further analysis." (PMID 34680287, 2021).
metastatic cancer (1 paper, 2021). A carcinoma which has spread from the original site of growth to another anatomic site. "In conclusion, BACH1 is a useful therapeutic target for metastatic cancer, as highlighted by recent publications." (PMID 33809182, 2021). "Furthermore, inhibiting BACH1 downstream targets such as mitochondrial metabolic pathways, glycolysis pathways, heme regulatory pathways, and redox homeostasis might be a highly insightful approach to manage metastatic cancer in a complex and context-dependent tumor microenvironment." (PMID 33809182, 2021).
ovarian clear cell cancer (1 paper, 2020). An invasive malignant neoplasm that arises from the ovary and is characterized by a predominance of clear and hobnail malignant epithelial cells. "Chromatin immunoprecipitation (ChIP) was performed on human ovarian clear cell carcinoma ES2 cells, overexpressing BACH1 tagged with a human influenza HA tag." (PMID 32132179, 2020).
primary hypertension (1 paper, 2020). "Indeed, primary hypertension was associated with increased expression of Nrf2 inhibitors, such as Keap1 and Bach1, which in turn, was correlated with low expression of Nrf2 and HO-1." (PMID 32664225, 2020). "The opposite effects were observed after the chronic administration of URB597 to rats with primary hypertension resulted in an increase in levels of Nrf2 and HO-1, and a decrease in levels of Bach1." (PMID 32664225, 2020).
pulmonary tuberculosis (1 paper, 2024). A bacterial infection that affects the lungs and is caused by Mycobacterium tuberculosis. "We found that BACH1 expression is associated clinically with active pulmonary tuberculosis." (PMID 38066332, 2024).
sarcopenia (1 paper, 2020). Progressive decline in muscle mass due to aging which results in decreased functional capacity of muscles. "Therefore, our results suggest that Bach1 may also be involved in sarcopenia." (PMID 32776961, 2020).
thalassemia (1 paper, 2022). An inherited blood disorder characterized by a decreased synthesis of one of the polypeptide chains that form hemoglobin. "Other regulatory pathways, including those of heme-regulated inhibitor kinase (HRI), iron-regulatory proteins (IRPs), and the heme-binding protein Bach1, are known to be either activated or suppressed in thalassemia cells." (PMID 35092867, 2022).
tuberculosis (1 paper, 2024). A chronic, recurrent infection caused by the bacterium Mycobacterium tuberculosis. "Together, these findings provide important evidence supporting and further delineating the role of lipid peroxidation-mediated cell death and tissue necrosis in Mtb infection while implicating Bach1 as a potential target for host-directed therapy in tuberculosis." (PMID 38066332, 2024). "In the case of TB, we observed elevated BACH1 mRNA expression in infected individuals who later progress to active tuberculosis, suggesting its use as a biomarker for disease risk." (PMID 38066332, 2024).
xeroderma pigmentosum group D (1 paper, 2017). Any xeroderma pigmentosum in which the cause of the disease is a mutation in the ERCC2 gene. "DinGEc is a structure-specific enzyme, related to human xeroderma pigmentosum group D (XPD), FANCJ, also known as BACH1, as well as to Saccharomyces cerevisiae Rad3 and Chl1, and Schizosaccharomyces pombe Rad15." (PMID 29121674, 2017).
cancer (99 papers, 2005 to 2026). A tumor composed of atypical neoplastic, often pleomorphic cells that invade other tissues. "Dysregulated BACH1 activity has been implicated in a range of pathologies, including chronic inflammatory diseases, fibrosis, and cancer, making it a promising therapeutic target." (PMID 42085862, 2026). "In many tumors, BACH1 is positively correlated with multiple immune cells, especially macrophages, monocytes, neutrophils, cancer-associated fibroblasts, myeloid dendritic cells, and regulatory T cells." (PMID 38321558, 2024). "An increase in NRF2 content increases the expression of heme oxygenase-1 (HO-1) and BTB domain and CNC homology 1 (BACH1) and the related factors associated with cancer tumor invasion and metastasis." (PMID 38385979, 2024). "Together, our results explain the emergent dynamics of underlying GRN that can underlie the observed antagonistic behaviour of RKIP and BACH1 in a pan-cancer manner." (PMID 37963558, 2023). "Together, these results suggest that RKIP and BACH1 show antagonistic trends in a pan-cancer manner; RKIP associates with an epithelial phenotype while BACH1 with a mesenchymal phenotype." (PMID 37963558, 2023). "To examine how RKIP and BACH1 associated with ferroptosis, we calculate the ssGSEA scores of a ferroptosis-based gene signature in cancer." (PMID 37963558, 2023). "This study also demonstrated that the rs372883C allele in the 3′-untranslated region (3′-UTR) of Bach1 resulted in evidently higher BACH1 levels than the rs372883T allele in both cancer and normal tissues." (PMID 37228820, 2023). "The ssGSEA score of KS-Epi signature correlated positively with RKIP levels in only 15 cancer types and negatively with BACH1 expression in 14 cancer types, thus indicating a rather ambivalent association." (PMID 37963558, 2023). "We analyzed the BACH1 mutation frequency and mutation sites of patients in different cancer types using cBioPortal." (PMID 35651942, 2022). "The tumor mutation burden (TMB) in four cancer species and up to six tumor infiltrated immune cells had a significant relevance with BACH1." (PMID 35651942, 2022). "BACH1 promotes the invasion and metastasis of cancer cells and is also associated with the poor prognosis of cancer patients with TNBC or lung tumors." (PMID 35406740, 2022). "We calculated the tumor mutation burden (TMB) of pan-cancer samples in the TCGA database and explored its relevance to BACH1 expression." (PMID 35651942, 2022). "The transcription factor BACH1 is a potential therapeutic target for a variety of chronic conditions linked to oxidative stress and inflammation, as well as cancer metastasis." (PMID 35313207, 2022). "BACH1 binds the tumor suppressor BRCA1 such that BACH1 mutation leads to defects in DNA repair that contribute to numerous forms of cancer." (PMID 35456431, 2022). "Cancer cells are expected to exploit dynamic changes in gene expression caused by the flexible amount or activity of BACH1, which can be altered in response to oxidative and other stresses, for their progression and survival." (PMID 34339740, 2021). "Furthermore, in BACH1-deficient cells, metformin, rotenone and antimycin A significantly repress cell growth and viability, meaning that BACH1 deficiency can effectively overcome cancer resistance to these drugs." (PMID 38321558, 2024). "Finally, we observed that low RKIP levels and upregulated BACH1 levels associated with worse clinical outcomes in many cancer types." (PMID 37963558, 2023). "Subsequently, we analyzed the prognosis of BACH1 mutations in different cancer types." (PMID 35651942, 2022). "The mutation sites of BACH1 varied in different cancer types and correlated to patients’ prognoses." (PMID 35651942, 2022). "Bach1 is a transcription factor activating glycolysis and increasing proliferation and metastatic potential in cancer cells." (PMID 41912851, 2026).
cancer (continued). "BACH1 also regulates cancer cell metabolism beyond fatty acids, including the production of lactate via hexokinase 2 (HK2)." (PMID 39467637, 2025). "The antioxidant treatment eliminates low levels of ROS and enhances angiogenesis gene expression in cancer cells, xenograft tumors, and tumor organoids in a BACH1-dependent manner under normoxic conditions." (PMID 40563308, 2025). "Our analysis of 30 published BACH1 target genes shows little overlap of regulated genes in response to BACH1 depletion across four cancer cell lines." (PMID 40716152, 2025). "This discrepancy is possible because BACH1 inhibits angiogenesis genes in endothelial cells while increasing angiogenesis genes in cancer cells." (PMID 39887888, 2025). "BACH1 plays a central role in cancer metastasis across various types, suggesting its wide relevance." (PMID 39887888, 2025). "Mechanistically, PLK1 stabilizes BTB domain and CNC homolog 1 (BACH1), which serves as a crucial transcription factor for genes involved in cancer metabolism and metastasis." (PMID 41284701, 2025). "BACH1 is overexpressed in various tumour types correlating with poor prognosis and recurrence [,20,22], it promotes cancer cell invasion (in vitro) [15,16,18,20,] and metastasis (in vivo)." (PMID 40716152, 2025). "BACH1 is a transcriptional repressor that regulates oxidative stress and inflammatory responses and has emerged as a promising therapeutic target in cancer and other diseases." (PMID 40716152, 2025). "Physiological functional roles of BACH1 include intracellular heme homeostasis, redox regulation, ferroptosis, and metabolic regulation in cancer cells." (PMID 40710214, 2025). "This pattern hints at a potential link between increased BACH1 expression and the progression of cancer metastasis." (PMID 38838145, 2024). "Inhibition of BACH1 has been shown to decrease antioxidant‐induced glycolysis rates and reduce migration and invasion of cancer cells." (PMID 38501838, 2024). "BACH1 promotes the malignancy of cancer cells, including metastasis, in breast cancer, pancreatic ductal adenocarcinoma, and lung cancer." (PMID 38673728, 2024). "The regulation of ECM remodeling by BACH1 is a novel approach to cancer treatment, which merits further research." (PMID 38321558, 2024). "By positively regulating the expression of multiple pro-metastatic genes, BACH1 has been shown to promote cancer cell invasiveness." (PMID 38895309, 2024). "These multiple functions of BACH1 in hematopoietic and cancer cells point to the importance of BACH1 regulation and suggest the presence of mechanisms for BACH1 regulation other than heme." (PMID 38673728, 2024). "It will be an important issue to understand how the balance of the two mechanisms of TBK1-mediated regulation of BACH1 is coordinated or switched in the context of iron metabolism, hematopoiesis and immune response, and cancer progression." (PMID 38673728, 2024). "BACH1 has a dual impact on cancer, which affects the accuracy and efficiency of targeted drug delivery." (PMID 38321558, 2024). "More importantly, BACH1 is highly expressed in and plays a key role in numerous malignant tumors, affecting cellular metabolism, tumor invasion and metastasis, proliferation, different cell death pathways, drug resistance, and the tumor microenvironment." (PMID 38321558, 2024). "As a potential antitumor strategy, small molecule inhibitors of BACH1 are also being explored in cancer." (PMID 38321558, 2024). "This review aims to highlight the research status of BACH1 in malignant tumor behaviors, and summarize its role in immune regulation in cancer." (PMID 38321558, 2024). "Taken together, these studies show that BACH1 is a potential metabolism-targeting therapy for cancer." (PMID 38255314, 2024).